BMX (BMX non-receptor tyrosine kinase)
Diseases named in the same sentence as BMX in open-access papers (continued):
Sharing a sentence is not in itself a finding about the gene and the disease.
Arthritis (2 papers, 2016 to 2017). Inflammation of a joint. "BMX genetic ablation in mutant mice resulted in protection from arthritis, suggesting that its up-regulation in the elderly blood cells contribute to the onset of chronic inflammation and may represent a novel therapeutic target in contexts outside of cancer." (PMID 27545843, 2016). "The first irreversible BTK kinase inhibitor PCI-32765, which has demonstrated the proof-of-concept for the anti-arthritis efficacy by direct inhibition of BTK kinase, also bears potent activities against BLK, BMX, EGFR, Her2, ITK, JAK3, TEC and others." (PMID 28352114, 2017).
bladder cancer (2 papers, 2017). "A previous study reported that overexpression of BMX in bladder cancer cells elevated the activity of AKT and STAT3, whereas knockdown of BMX had the opposite effect." (PMID 28514765, 2017). "BMX is up-regulated in bladder cancer and predicts poor prognosis in patients with cystectomy." (PMID 28422715, 2017).
cervical cancer (2 papers, 2017 to 2018). A primary or metastatic malignant neoplasm involving the cervix. "All of these results suggested that BMX promoted the proliferation of cervical cancer cells by decreasing the number of cells in G0/G1 phase and increasing the number of cells in S or G2/M phase." (PMID 28514765, 2017). "Western blotting was used to detect the expression of BMX in cervical cancer cell lines, and a high level of BMX expression was observed in HeLa, SiHa, HT-3 and CaSki cells, and a low level of BMX expression was observed in C-33A cells." (PMID 28514765, 2017). "This can support the idea that BMX needs to cooperate with other pathways in vivo tumorigenesis of cervical cancer cells." (PMID 28514765, 2017). "These suggesting that knockdown of BMX expression in cervical cancer cells can attenuate cell proliferation and viability." (PMID 28514765, 2017). "In this study, we showed that BMX expression exhibits a gradually increasing trend from normal cervical tissue to cervical cancer in situ and then to invasive cervical cancer tissue." (PMID 28514765, 2017). "In conclusion, our studies have found BMX can promote cell proliferation and tumorigenesis in cervical cancer cells, thus the development of BMX inhibitors, like BMX-IN-1, is necessary for cervical cancer therapy." (PMID 28514765, 2017). "All of these results suggested that BMX promotes the proliferation of cervical cancer cells by activating the PI3K/AKT/mTOR and STAT3 pathways." (PMID 28514765, 2017). "All of these results indicated that BMX was increased in cervical carcinoma and strongly suggested that BMX must be related to cervical carcinogenesis." (PMID 28514765, 2017). "The expression of BMX was significantly higher in cervical carcinoma tissues than in normal cervical tissues (p < 0.01)." (PMID 28514765, 2017). "Knockdown of BMX in HeLa and SiHa cervical cancer cell lines using two different silencing technologies, TALEN and shRNA, inhibited cell growth in vitro and suppressed xenograft tumor formation in vivo, whereas overexpression of BMX in the cell line C-33A significantly increased cell proliferation." (PMID 28514765, 2017). "Furthermore, a western blot was used to analyze the expression of BMX in 6 normal cervical and 7 cervical cancer tissues, all of which were selected randomly." (PMID 28514765, 2017). "However, the function of BMX in cervical cancer is still poorly understood." (PMID 28514765, 2017). "In this study, we aimed to explore the role of BMX during the development and progression of cervical cancer, and we are the first to report that BMX can promote cell proliferation and tumor formation in cervical cancer by activating PI3K/AKT and STAT3 signaling pathways." (PMID 28514765, 2017). "All of these data indicated that BMX could promote the proliferation of cervical carcinoma cells." (PMID 28514765, 2017).
injury (2 papers, 2014 to 2017). Damage inflicted on the body as the direct or indirect result of an external force, with or without disruption of structural continuity. "Our previous data have shown that the expression of BMX is 1.8- to 2.5-fold higher in rats with induced traumatic brain injury than in naïve rats." (PMID 24860816, 2014). "Consistent with earlier studies, the increased APP, GFAP and BMX metabolites are observed following brain injury using similar Marmarou acceleration weight drop model or other experimental TBI models, such as controlled cortical impact or fluid percussion models of brain injury." (PMID 28552947, 2017).
ischemia (2 papers, 2014 to 2018). A hypoperfusion of the BLOOD through an organ or tissue caused by a PATHOLOGIC CONSTRICTION or obstruction of its BLOOD VESSELS, or an absence of BLOOD CIRCULATION. "In our previous studies, we found that BMX induces activation by H2O2 in primary cortical neurons and plays an important role in ischemia-induced cell death." (PMID 29419747, 2018).
lung adenocarcinoma (2 papers, 2017 to 2024). A carcinoma that arises from the lung and is characterized by the presence of malignant glandular epithelial cells. "We here identified a BMX skipping isoform through the analyses of Exon1.0 array profiling of human lung adenocarcinoma samples in combination with RACE method." (PMID 28422715, 2017). "BMXΔN, resulting from exon skipping with excluding exon 1 to exon 8 of BMX gene, was found in 12% human lung adenocarcinoma specimens." (PMID 28422715, 2017). "Through bioinformatics analyses of Exon1.0 array data from Chinese lung adenocarcinoma and 5′ RACE, we identified a novel BMX skipping variant." (PMID 28422715, 2017). "Interestingly, when we use F8/R12 primers to detect the levels of BMX mRNA in BMXΔN positive lung adenocarcinomas, we found very low expression of BMX or even no expression of BMX in these lung adenocarcinomas (data not shown)." (PMID 28422715, 2017). "However, the transcript of BMX was different between BMXΔN positive lung adenocarcinomas and adjacent non-tumour specimens." (PMID 28422715, 2017). "Here, we present evidence that BMX was not up-regulated in lung adenocarcinomas." (PMID 28422715, 2017).
lung carcinoma (2 papers, 2017 to 2022). "This molecule regulates multidrug resistance in lung cancer through the PI3K/BMX/STAT3 signaling pathway." (PMID 36106335, 2022). "Collectively, this study discovered a novel BMX skipping with crucial function in lung cancer cells." (PMID 28422715, 2017). "However, the alternative splicing of BMX and its clinical relevance in lung cancer remain to be elucidated." (PMID 28422715, 2017).
neuroblastoma (2 papers, 2024 to 2025). Neuroblastoma (NB) is the most common solid, extracranial childhood tumor. "Comparison of neuroblastoma models identifies BMX as a marker of aggressive forms of the disease, suggesting potential as a therapeutic target." (PMID 39133652, 2024). "We next examined the role of MSI2 and BMX in neuroblastoma cell proliferation." (PMID 40103284, 2025). "NSC617570 reduces BMX expression, ERK phosphorylation, neuroblastoma cell proliferation in vitro and tumor progression in vivo." (PMID 40103284, 2025). "RT‐PCR, immunoblot and Alamar blue assays showed that forced MSI2 overexpression resulted in BMX mRNA and protein up‐regulation, ERK protein phosphorylation and neuroblastoma cell proliferation, and PRKCQ‐AS1 or BMX knockdown largely blocked the effects." (PMID 40103284, 2025). "RT‐PCR, immunoblot and Alamar blue assays showed that forced PRKCQ‐AS1 overexpression resulted in BMX mRNA and protein up‐regulation, ERK protein phosphorylation and neuroblastoma cell proliferation, and MSI2 or BMX knockdown largely blocked the effects." (PMID 40103284, 2025). "Compound NSC617570 blocks PRKCQ‐AS1 binding to MSI2, leading to BMX mRNA disassociation from MSI2 protein, BMX reduction, ERK dephosphorylation, neuroblastoma cell proliferation suppression in vitro and tumor growth inhibition in vivo." (PMID 40103284, 2025). "PRKCQ‐AS1 RNA interacts with MSI2 protein, resulting in the stabilization and overexpression of oncogenic mRNAs including BMX, ERK protein phosphorylation and neuroblastoma cell proliferation in vitro and tumor progression in vivo." (PMID 40103284, 2025). "Taken together, the data suggest that PRKCQ‐AS1 RNA interacts with MSI2 protein to up‐regulate BMX expression and augment ERK protein phosphorylation, leading to neuroblastoma cell proliferation." (PMID 40103284, 2025). "PRKCQ‐AS1 RNA forms a complex with MSI2 protein to induce BMX mRNA stabilization and overexpression, ERK protein phosphorylation and neuroblastoma cell proliferation." (PMID 40103284, 2025). "Conversely, PRKCQ‐AS1 knockdown reduced ERK protein phosphorylation and neuroblastoma cell proliferation, and transfection with an MSI2 or BMX expression construct largely reversed the effects." (PMID 40103284, 2025). "Consistent with data from PRKCQ‐AS1 or MSI2 knockdown, treatment with NSC617570 reduces BMX expression, ERK protein phosphorylation, neuroblastoma cell proliferation and clonogenic capacity." (PMID 40103284, 2025). "AlphaScreen of a compound library identifies NSC617570 as an efficient inhibitor of PRKCQ‐AS1 RNA and MSI2 protein interaction, and NSC617570 reduces BMX expression, ERK protein phosphorylation, neuroblastoma cell proliferation in vitro and tumor progression in mice." (PMID 40103284, 2025). "Overexpression of PRKCQ‐AS1 or MSI2 enhances BMX expression, ERK protein phosphorylation and neuroblastoma cell proliferation; MSI2 or BMX knockdown blocks the effects of PRKCQ‐AS1 overexpression; and PRKCQ‐AS1 or BMX knockdown blocks the effects of MSI2 overexpression." (PMID 40103284, 2025). "By contrast, using the median, low or upper quartile of PRKCQ‐AS1, MSI2 and BMX RNA expression as the cut‐off, Kaplan‐Meier survival analyses showed that high levels of PRKCQ‐AS1, MSI2 or BMX expression in MYCN‐amplified human neuroblastoma tissues did not correlate with poor patient prognosis." (PMID 40103284, 2025). "PRKCQ‐AS1 or MSI2 knockdown reduces, while its overexpression enhances, BMX mRNA stability and expression, ERK protein phosphorylation and MYCN nonamplified neuroblastoma cell proliferation." (PMID 40103284, 2025). "In human neuroblastoma tissues, high levels of PRKCQ‐AS1, MSI2 or BMX expression predict poor prognosis in MYCN nonamplified but not MYCN‐amplified patients." (PMID 40103284, 2025).
neuroblastoma (continued). "Taken together, the data demonstrate that PRKCQ‐AS1 interacts with MSI2 to enhance BMX expression, resulting in ERK protein phosphorylation and MYCN nonamplified neuroblastoma tumorigenesis, and that PRKCQ‐AS1 and MSI2 interaction is a valid therapeutic target." (PMID 40103284, 2025).
prostate tumors (2 papers, 2020 to 2024). "However, few previous studies have investigated the direct diagnostic role of BMX in cancer; one study reported that BMX expression was greater in colon, breast, and prostate tumors than in normal tissue, which contradicts our findings." (PMID 39347140, 2024).
renal cell carcinoma (2 papers, 2014 to 2023). "In addition, strong direct ibrutinib inhibition of epithelial and endothelial tyrosine kinase/bone marrow X kinase (ETK/BMX) may also play a role in renal cell carcinoma (RCC)." (PMID 37919668, 2023). "Expression of the non-receptor tyrosine kinase ETK/BMX has been reported in several solid tumors, but the underlying molecular mechanisms and its clinical significance in renal cell carcinoma (RCC) remain to be elucidated." (PMID 24606948, 2014).
adenoma (1 paper, 2022). A neoplasm arising from the epithelium. "Nine and fourteen of 20 patients had adenoma precursor cell population with high BMX and SH2D6 levels, respectively." (PMID 35221332, 2022). "Interestingly, in adenoma precursor cells, the genes that were hit in the PTK signaling also included the marker genes of adenoma precursor cells, such as BMX, MATK, and HCK." (PMID 35221332, 2022). "The results showed that BMX, HCK, and MATK were exclusively upregulated in the adenoma precursor cell population." (PMID 35221332, 2022). "Quantification of fluorescence intensity of double-positive cells showed that the levels of BMX, HCK, and MATK in adenoma were higher than those in normal tissues." (PMID 35221332, 2022). "Protein tyrosine kinases (PTKs) BMX and HCK were identified as potential drivers of adenoma initiation." (PMID 35221332, 2022). "Specific BMX and HCK upregulations were observed in adenoma precursor cell populations from normal and adenoma biopsies." (PMID 35221332, 2022). "We then validated these results by probing BMX, HCK, and MATK, along with epithelial marker E-cadherin, in biopsies from healthy donors, normal tissues, and patient-matched adenoma tissues." (PMID 35221332, 2022). "The BMX+ or HCK+ or MATK+ E-cadherin+ double-positive cells presented in both normal tissue and matched adenoma were observed in 8, 11, and 7 of 20 patients, respectively." (PMID 35221332, 2022). "Taken together, our results indicate that BMX and HCK promote colorectal epithelial cell proliferation and adenoma formation through the STAT3 signaling pathway." (PMID 35221332, 2022). "Notably, BMX or HCK alone drove the formation of polyp-like structures in organoid models, emphasizing their strong influence on adenoma initiation." (PMID 35221332, 2022).
Anxiety (1 paper, 2014). Intense feelings of nervousness, tension, or panic often arise in response to interpersonal stresses. "We examined whether the BMX SNPs were associated with the Beck anxiety inventory (BAI) and Beck depression inventory (BDI) scores." (PMID 24860816, 2014).
atherosclerosis (1 paper, 2025). A disease characterized by the build-up of fatty material and calcium deposition in the arterial wall resulting in partial or complete occlusion of the arterial lumen. "Theoretically, BMX inhibition could disrupt endothelial homeostasis and vascular repair, given its role in atherosclerosis and myocardial remodeling models." (PMID 41567642, 2025).
Atherosclerotic lesion (1 paper, 2016). A lesion associated with atherosclerosis, a multifactorial and multipart progressive disease manifested by the focal development within the arterial wall of lesions, that ranges from the development of a fatty streak, plaque progression, and plaque disruption. "In contrast to the pro-angiogenic effect in the ischemic myocardium, TXL treatment substantially attenuated VV neovascularization in murine advanced atherosclerotic lesions by inhibiting inflammatory angiogenesis via BMX/NF-κB/MAPK pathways, leading to enhanced plaque stabilization." (PMID 26908443, 2016).
colon cancers (1 paper, 2024). "In contrast, an earlier study documented that elevated BMX expression in aggressive cancers such as prostate, breast, and colon cancers is linked to heightened apoptosis resistance and poorer patient survival outcomes, indicating that the role of BMX in cancer may be complex and context-dependent." (PMID 39347140, 2024).
endometrial cancer (1 paper, 2024). Primary or metastatic malignant neoplasm involving the endometrium (mucous membrane that lines the endometrial cavity). "Using the TCGA dataset, BMX mutation had occurred in 2% of the samples that were tested (10967 samples from 32 studies); the majority of BMX mutations occurred in endometrial cancer with 7.18% (38 patients) mutations and 0.57% (3 patients) deep deletions." (PMID 39347140, 2024).
endometriosis (1 paper, 2019). The growth of functional endometrial tissue in anatomic sites outside the uterine body. "In addition to its aid in the survival of the endometriosis cells, an investigation conducted to examine the relationship between EPHA3 and the expression of signaling proteins flagged the suppression of several signaling proteins, including PI3K, STAT3 and BMX as a result of EPHA3 overexpression." (PMID 31262977, 2019).
head and neck squamous cell carcinoma (1 paper, 2024). A squamous cell carcinoma that arises from any of the following anatomic sites: lip and oral cavity, nasal cavity, paranasal sinuses, pharynx, larynx, and salivary glands. "We also found that the expression of BMX in head and neck squamous cell carcinoma (HNSC) patients who had human papillomavirus (HPV) infection was significantly lower than that in HNSC patients without HPV infection." (PMID 39347140, 2024).
Hypertension (1 paper, 2025). The presence of chronic increased pressure in the systemic arterial system. "Whether the cardiovascular toxicities observed clinically with ibrutinib, particularly hypertension, which may involve endothelial dysfunction, are partially attributable to BMX inhibition represents an open question warranting further investigation." (PMID 41567642, 2025).
leukemia (1 paper, 2010). A malignant (clonal) hematologic disorder, involving hematopoietic stem cells and characterized by the presence of primitive or atypical myeloid or lymphoid cells in the bone marrow and the blood. "Albeit having a role in the formation of leukemia, our research is the first to demonstrate that BMX may play a significant role in the regulation of prostate CSCs." (PMID 20929579, 2010).
melanoma (1 paper, 2020). A malignant, usually aggressive tumor composed of atypical, neoplastic melanocytes. "Furthermore, the BMX and CFAP47 variants were found in homozygosity in a healthy control, thus being excluded, as familial melanoma susceptibility is consistent with autosomal dominant inheritance." (PMID 32276436, 2020).
myeloid leukemia (1 paper, 2016). A clonal proliferation of myeloid cells and their precursors in the bone marrow, peripheral blood, and spleen. "BMX is expressed in hematopoietic progenitor cells and myeloid leukemias and has been found to mediate STAT3 activation and subsequent transformation by Src." (PMID 26624983, 2016).
sarcoma (1 paper, 2024). A usually aggressive malignant neoplasm of the soft tissue or bone. "As expected for a BMX-dependent effect in our NB models, neither sarcoma spheroid models showed changes in cell viability and sphere size upon BMX inhibition." (PMID 39133652, 2024).
Stroke (1 paper, 2019). Sudden impairment of blood flow to a part of the brain due to occlusion or rupture of an artery to the brain. "A predictive model with 89.6% accuracy was identified using 6 network-central and differentially expressed genes (ID3, MBTPS1, NOG, SFXN2, BMX, SLC22A1), characterized by large differences in association network connectivity between stroke and control samples." (PMID 31391037, 2019). "The mRNAs of ID3, MBTPS1, NOG, and SFXN2 have lower concentrations (are down-regulated) in the stroke samples (log FC = − 0.915, − 0.356, − 0.752, − 0.301, respectively) while BMX and SLC22A11 are up-regulated (log FC = 0.456, 0.365) in the stroke patients." (PMID 31391037, 2019). "In contrast, the connectivity of the other 5 genes is higher in the stroke vs. control networks: for MBTPS1, the control and stroke d = 1 neighborhoods have 20 vs. 49 genes, respectively, for NOG 13 vs. 65, for SFXN2 42 vs. 62, for BMX 22 vs. 61, and for SLC22A1, 15 vs. 63 neighbors." (PMID 31391037, 2019). "Expression values from the genes ID3, MBTPS1, NOG, SFXN2, BMX, and SLC22A1 can jointly distinguish stroke from non-stroke samples with a high level of accuracy: 89.6% of samples are correctly classified in cross-validation sampling." (PMID 31391037, 2019).
synovial sarcoma (1 paper, 2024). "In order to assess the specificity of the BMX-IN-1 inhibitor, we applied similar experimental conditions to primary spheroid cultures derived from 2 other pediatric tumors, Ewing and Synovial sarcoma, which displayed very low BMX expression levels." (PMID 39133652, 2024).